CTSB (cathepsin B)
Diseases named in the same sentence as CTSB in open-access papers (continued):
Sharing a sentence is not in itself a finding about the gene and the disease.
kidney diseases (continued). "The detection of CTSB may be a method for the early diagnosis of kidney disease, and CTSB-targeted treatment can effectively slow the progression of kidney disease." (PMID 40129990, 2025). "As another example, cg21919729, located within the CTSB gene and identified by our single-site analysis, did not have its methylation reported to be associated with kidney disease." (PMID 37188670, 2023). "The prominent cytoplasmic release of cathepsin B in tubular epithelial cells is crucial for tubular cell injury and the activation of a cytoplasmic macromolecular complex involved in the progression of kidney diseases." (PMID 34575364, 2021). "Studies conducted on animals showed that cathepsin B is involved in kidney diseases." (PMID 34575364, 2021). "CTSB may be involved in complex renal diseases by mediating/regulating two or more types of PCD." (PMID 40129990, 2025). "CTSB may not singularly mediate/regulate a certain PCD-induced renal disease during the progression of renal disease." (PMID 40129990, 2025). "Current research does not provide direct evidence that CTSB can induce kidney disease by directly mediating autophagic cell death, but CTSB may play a role in kidney disease by regulating autophagy." (PMID 40129990, 2025). "Interestingly, our analysis identified several previously unidentified CpG sites associated with baseline eGFR with nearby genes having differential expression between samples from people with and without kidney disease, such as RFTN1 and CTSB (“Discussion”)." (PMID 37188670, 2023).
infectious disease (7 papers, 2015 to 2023). A disorder directly resulting from the presence and activity of a microbial, viral, or parasitic agent in humans. "However, when lysosomal membrane permeabilization increases in inflammatory or infectious diseases, CTSB can be overactivated and released from the lysosome." (PMID 37307830, 2023).
brain diseases (4 papers, 2013 to 2023). "Chronic neuroinflammation is a hallmark of PD pathophysiology, and microglial cathepsin B has been proposed as a key driver of inflammatory brain diseases and brain ageing." (PMID 37958596, 2023). "The neuropathology of AD, traumatic brain injury, and other related brain disorders have all been linked to cathepsin B, according to extensive research from Hook’s lab." (PMID 37958596, 2023). "Elevated levels of cathepsin B have been detected in biological fluids of patients with brain diseases." (PMID 37138705, 2023). "This highlights the variability of brain disease, but it also shows that vascular leak changes accompany cathepsin B changes as would be expected given that BBB compromise generally accompanies neuroinflammation." (PMID 24237884, 2013).
vasculopathy (4 papers, 2012 to 2025). "Enhanced expression of endothelial cathepsin B and cathepsin L due to Fli1 deficiency has been shown to be associated with SSc vasculopathy, whereas downregulation of CTSB, CTSL, and CTSV in dermal fibroblasts implicates in SSc dermal fibrosis." (PMID 36768203, 2023). "Based on the previous report that implicated lysosomal enzyme cathepsin B as a potential contributor to the development of SSc vasculopathy, we focused on its role in FLI1 and ERG protein degradation." (PMID 32979864, 2021). "CTSB is potentially associated with the disease process of SSc, especially fibrosis and vasculopathy." (PMID 22384200, 2012). "Since the deficiency of transcription factor Fli1 in endothelial cells is potentially associated with the development of SSc vasculopathy, cutaneous CTSB expression was evaluated by immunostaining in Fli1+/− and wild type mice as well as in SSc and control subjects." (PMID 22384200, 2012). "In conclusion, up-regulation of endothelial CTSB due to Fli1 deficiency may contribute to the development of SSc vasculopathy, especially digital ulcers, while reduced expression of CTSB in lesional dermal fibroblasts is likely to be associated with skin sclerosis in early dcSSc." (PMID 22384200, 2012). "Collectively, these results suggest that elevation of CTSB contributes to the pathological process leading to SSc vasculopathy, especially to digital ulcers in dcSSc." (PMID 22384200, 2012).
Colon (2 papers, 2023 to 2024). "This indicates the potential importance of cathepsin B in digestive system tumors, which warrants further investigation." (PMID 38590662, 2024). "This analysis encompassed a total of nine cathepsins include cathepsin B, cathepsin E, cathepsin F, cathepsin G, cathepsin H, cathepsin L2, cathepsin O, cathepsin S, and cathepsin Z, and six digestive system tumors (HCC, PCa, BTC, CRC, GC, and EC)." (PMID 38590662, 2024).
metabolic disease (2 papers, 2024 to 2025). A congenital disorder (due to inherited enzyme abnormality) or acquired (due to failure of a metabolically important organ) disorder resulting from an abnormal metabolic process. "In metabolic disease, alterations in CTSB expression or activity have been reported in muscle and brain, although the direction and magnitude of these changes remain inconsistent across studies." (PMID 41305665, 2025). "Interventions such as aerobic exercise and dietary modulation have been shown to increase CTSB levels, and these responses may contribute to the maintenance of both muscle function and cognitive health in metabolic disease." (PMID 41305665, 2025).
CNS tumors (1 paper, 2021). "Quantitative research has revealed upregulated levels of other proteases such as uPA (a serine protease) and its receptor uPAR as well as cathepsin B (a cysteine protease) in CNS tumors." (PMID 34638718, 2021).
CTSB also shares sentences with these, for which no sentence is quoted: allergies (7 papers); type 2 diabetes (7); periodontal disease (5); adenocarcinoma (4); autoimmune disease (4); clonorchiasis (4); colon adenocarcinoma (4); Huntington disease (4); amebiasis (3); benign tumors (3); immune disorders (3); Lysosomal disease (3); multiple myeloma (3); Nephropathy (3); nephrotic syndrome (3); paragonimiasis (3); Parkinsonism (3); steatosis (3); Atopic Dermatitis (2); bone cancer (2); breast adenocarcinoma (2); Cachexia (2); Calpainopathies (2); central nervous system diseases (2); cerebral amyloid angiopathy (2); chronic obstructive pulmonary disease (2); chronic periodontitis (2); ciliopathies (2); echinococcosis (2); head and neck squamous cell carcinoma (2).
A further 160 diseases each share a sentence with CTSB in 2 papers or fewer.